KRAS (KRas proto-oncogene, GTPase)
Diseases named in the same sentence as KRAS in open-access papers (continued):
Sharing a sentence is not in itself a finding about the gene and the disease.
cancer (continued). "The miRNA-based germline pathogenic variants of which the inherited KRAS-variant is the first example, are a compelling class of biomarkers that may ultimately help us dramatically improve our approach to cancer therapy." (PMID 37728512, 2023). "76% of Ras-mutant cancer patients harbor KRAS mutations versus only 7% with HRAS mutations." (PMID 36864243, 2023). "We therefore propose that KRAS mutation status could serve as a biomarker for anti-CD47 cancer immunotherapy." (PMID 36413402, 2023). "In addition to KRAS activating mutations, an imbalance between wt and mut KRAS alleles can influence cancer cells’ fitness, expression profile and therapy response in LUAD and PDAC." (PMID 37210549, 2023). "Alterations in the KRAS isoform account for 75–85% of RAS-mutant cancers, with mutations at G12 accounting for 81% of these, and are mainly associated with non-small cell lung cancer (NSCLC), colorectal cancer (CRC), and pancreatic ductal adenocarcinoma (PDAC)." (PMID 36864508, 2023). "As such, concurrent targeting of various forms of mutant KRAS and individual members of the miRNA biogenesis and processing machinery might represent a synergistic therapeutic strategy to treat several types of cancer with KRAS mutation." (PMID 37686149, 2023). "Therefore, whilst the evidence for Ras dosage influencing tumorigenesis is compelling, the proposed rare codon link between KRAS and cancer mutation patterns remains contentious." (PMID 36864243, 2023). "The different allele frequencies in different cancer types may be due to several factors, including the role of the KRAS gene in different signaling pathways and the intracellular environment in which mutations occur." (PMID 37174676, 2023). "Furthermore, efficacy of SHP2 inhibition with MAPK therapy has been reported in cancers with KRAS mutation." (PMID 36752207, 2023). "KRAS signaling is associated with cancer progression in many cancers." (PMID 37274025, 2023). "Given that single drugs elicit limited antitumour responses in KRAS-mutated cancers, in part due to resistance mechanisms, this study proposes the combination of JAK2i with the recently FDA-approved KRASG12Ci Sotorasib based on a notable synergistic effect in vitro and in vivo." (PMID 37210549, 2023). "KRAS is a commonly encountered mutated oncogene in human cancers." (PMID 38067288, 2023). "KRAS mutations are one of the most common driver mutations in cancer." (PMID 36810451, 2023). "Although they have equivalent levels of canonical RAS signaling, KRAS causes more cancer than HRAS." (PMID 36975494, 2023). "This constitutive signaling is a hallmark of KRAS-mutated cancers." (PMID 38203635, 2023). "Moreover, KRAS possesses considerable post-transcriptional modifications, binding tightly to GTP, making the blockage of its hyperactivation difficult in the case of KRAS-mutated cancers." (PMID 37376135, 2023). "Considering the wide use of anti-PD-1 antibodies in clinical treatment of multiple solid tumors, future investigations of 1-2C TCR-T cells in combination with anti-PD-1 antibodies may be promising for cancer patients with the KRAS-G12V mutation." (PMID 37828002, 2023). "The KRAS-variant is the first functional, inherited miRNA-disrupting variant identified in cancer." (PMID 37728512, 2023). "A higher proportion of variant than wild-type KRAS tumors were seen for stage IV for YO (1025 patients [66.3%] vs 1421 patients [61.9%]; P = .03) and LO (4358 patients [59.6%] vs 5416 patients [51.5%]; P < .001) cancers." (PMID 38032636, 2023). "SHP2 inhibition is strongly synergistic with MEK or ERK inhibition in KRAS-mutated cancers." (PMID 37569406, 2023). "The G12C mutation may be the most common in NSCLC—but it is a minority of KRAS alleles across all other cancers." (PMID 36933199, 2023).
cancer (continued). "KRAS mutations are found at different rates in a variety of cancers." (PMID 37110848, 2023). "Mutation in the KRAS gene is frequently associated with human cancers, with 90% found in PC." (PMID 36635659, 2023). "Importantly, MEK inhibitors increase the metabolic dependency of cancer cells on autophagy in the presence of KRAS mutations." (PMID 37894382, 2023). "Inhibition of KRAS signaling could therefore render cancer cells more susceptible to immune attack by both T cells and macrophages, which might contribute to the overall antitumor effect of KRAS inhibitors in vivo." (PMID 36413402, 2023). "Furthermore, knockdown of HSPA5 via siRNA reduced the oncogenic KRAS protein level in various KRAS mutated cancers." (PMID 37189349, 2023). "Moreover, the get-dPCR technique demonstrated the ability to distinguish single-base mutations with extreme clarity, as exemplified in the detection of three cancer mutations, KRAS c.35G > T, BRAF c.1391G > T, and BRAF c.1799T > A." (PMID 37686219, 2023). "However, KRAS mutation is less common in the setting of MSI, and as was demonstrated in the Keynote-164 trial, KRAS-mutated MSI cancers confer a lower objective response compared to KRAS-wildtype cancers." (PMID 37190303, 2023). "The inhibition of the other MAPK pathway components can indirectly target KRAS-mutated cancers." (PMID 37190303, 2023). "The biologic role of the KRAS p.G12C mutation varies among different types of cancers." (PMID 37509241, 2023). "The three human Ras genes, HRAS, KRAS, and NRAS, are found frequently mutated in about one-third of human cancers, with KRAS mutations being the most prevalent among the three isoforms (∼86% of cases), and with NRAS and HRAS representing only 11% and 3%, respectively." (PMID 38051103, 2023). "Specifically, mutations of KRAS G12C, G12D, and G12V are frequent in human cancers." (PMID 37513471, 2023). "The effect of our prototypes in other types of cancers carrying G12V KRAS mutations also remains to be tested, maybe leading to a better prognosis in less immunosuppressive environments." (PMID 37122717, 2023). "We searched PubMed using the terms “pancreatic AND cancer AND KRAS AND mutation” and meeting abstracts from the American Society of Clinical Oncology (ASCO), the European Society of Medical Oncology (ESMO), and the American Association for Cancer Research (AACR) annual meetings from 2015 to 2023." (PMID 37894382, 2023). "Also, we were interested in determining if there are differences in the interactome of these mutants in different cell lines and, in particular, in a cancer type where KRAS is commonly mutated." (PMID 37627169, 2023). "A BRAF mutation was detected in the first blood draw, a subsequent sample indicated remission, and then a new pathogenic mutation in KRAS was detected in a third blood draw, suggesting cancer recurrence, which could prompt clinical staff for further follow-up." (PMID 37218906, 2023). "Additionally, multiple de novo CTC-exclusive mutations have been identified in genes that are associated with human cancers, namely, KRAS, BRAF, and PIK3CA." (PMID 36980717, 2023). "To verify whether CTC-like cells were truly cancer cells, we performed single-cell mutation analyses of the KRAS, BRAF, and PIK3CA genes." (PMID 36672711, 2023). "Also, KRAS mutation, the second most common in our sample, belongs to the family of genes most frequently present in human cancers." (PMID 36986526, 2023). "Why is KRAS mutated instead of other RAS isoforms in cancer?" (PMID 37158894, 2023). "Although substantial research focused on metabolic changes has improved the understanding of KRAS-mutation-driven cancers, the precise mechanism by which metabolic reprogramming promotes and coordinates KRAS-mutant CRC growth and progression remains to be fully investigated." (PMID 37937641, 2023).
cancer (continued). "Given the recent advances in clinical trials to directly target KRAS and GNAS mutations in other cancers, we propose a rationale to explore targeting KRAS G12C and G12D, and GNAS R201H and R201C in pre-clinical studies in PMP to produce preliminary results supporting a future clinical trial." (PMID 36723696, 2023). "KRAS variant distribution was different in the case of benign and carcinoma samples." (PMID 36765865, 2023). "Of the 6 carcinomas of unknown origin, 2 cases showed a KRAS G12D/V variant and one case showed an amplification of the same gene." (PMID 36125633, 2023). "A notable example is the therapies for KRAS mutated carcinomas." (PMID 38057859, 2023). "However, basal extrusion is a hallmark of beginning dissemination and metastasis in carcinoma, especially KRas mutated carcinoma cells." (PMID 36517670, 2023). "KRAS-G12V is a representative cancer driver mutation that can induce cancer in various tissues." (PMID 35982173, 2022). "Kirsten rat sarcoma (KRAS) gene is the most commonly mutated oncogene in human cancers." (PMID 35359599, 2022). "Since KRAS as one of the most frequently mutated oncogenes, it is mutated in approximately 25% of all human cancers, participating in more than 90% of pancreatic ductal adenocarcinomas (PDAC), approximately 30–40% of colon cancers (CRC), and 17% of non-small cell lung cancer (NSCLC)." (PMID 36430323, 2022). "KRAS is the major mutated isoform of the Ras gene in cancers, including in ∼85% of all cancers." (PMID 36479072, 2022). "Among them, KRAS is mutated more frequently in human cancer than any other oncogene." (PMID 36393833, 2022). "KRAS is the most frequently mutated oncogene identified in human cancers." (PMID 36012655, 2022). "KRAS mutations have been connected to metabolism and epigenetic regulation in several cancer types." (PMID 35888776, 2022). "Mutations in KRAS are known to be key drivers in some of the most lethal human cancers." (PMID 35753348, 2022). "Building upon this groundbreaking discovery, sotorasib (AMG510) obtained approval by the United States Food and Drug Administration in 2021 to become the first therapy to directly target the KRAS oncoprotein in any KRAS-mutant cancers, particularly those harboring the KRASG12C mutation." (PMID 35045886, 2022). "KRAS mutations have been shown to be the driver mutation for ~25% of human cancers, while most frequently present in pancreatic (98%) and colorectal (53%) cancers." (PMID 35886918, 2022). "Merck noted that future partnerships with Moderna remain focused on oncology, with the two companies continuing to work together to develop personalized cancer vaccines such as mRNA-4157 as well as cancer vaccines that encode the four most common KRAS mutations." (PMID 35517800, 2022). "Finally, the relative contribution of KRAS mutations and dysregulation of KRAS-related non-coding RNAs in the pathogenesis of human cancer should be clarified." (PMID 35139853, 2022). "This selective targeting of KRASG12C has left KRAS cancer patients driven by other mutations with unmet medical needs, spurring further search for inhibitors with novel mechanism of action to reversibly inhibit KRAS." (PMID 36273239, 2022). "Targeting immune-checkpoint molecules, such as programmed cell death 1 (PD-1), programmed cell death ligand 1 (PD-L1) and cytotoxic T-lymphocyte-associated protein 4 (CTLA-4), has also demonstrated to be one of the most promising cancer treatments, with positive results in KRAS-mutated cancers." (PMID 35883626, 2022). "Oncogenic activation of KRAS is implicated in many different cancers, mainly by mutations in KRAS." (PMID 36077521, 2022).
cancer (continued). "Among them, KRAS mutations account for 85% of observed RAS mutations in cancer." (PMID 36033504, 2022). "A recent study using next-generation sequencing technology to test cancer-related genes has shown that several targeted mutations (KRAS, PIK3CA, IRS2, Sox2, and HRR genes) may potentially become effective targeted treatment sites for patients." (PMID 35909972, 2022). "We recently reported that the dual blockade of asparagine bioavailability and macropinocytosis could represent a novel therapeutic strategy for KRAS-mutated cancers." (PMID 36291140, 2022). "KRAS mutations are considered the most common type of Ras mutations in all types of human cancers." (PMID 36532636, 2022). "KRAS, the oncogene mutated highly in cancers, is associated with poor prognosis of LUAD." (PMID 35574406, 2022). "KRAS mutations are one of the most commononcogenicdrivers in human cancer." (PMID 36001446, 2022). "KRAS is the most frequently mutated oncogene and drives the pathogenesis of several cancers." (PMID 36088370, 2022). "In addition to cancer Hallmark pathways, KRAS signaling is upregulated in R/R MMs but downregulated in ND MMs, indicating KRAS-mediated oncogenic signaling activation in MM progression." (PMID 36033464, 2022). "Indirect KRAS inhibition—targeting KRAS membrane associations and cancer vaccine." (PMID 36012655, 2022). "KRAS activity is often enhanced in cancers via hyperactivating mutations and gene amplification." (PMID 35546148, 2022). "KRAS mutations are among the most commonly occurring mutations in cancer." (PMID 36531078, 2022). "In cancer cells PHGDH upregulation could be driven by KRAS activating mutations, thus we tested whether such mechanism would also take place in CCA cells." (PMID 35619118, 2022). "Most studies on macropinocytosis in cancer focus on tumors with oncogenic KRAS mutations." (PMID 35177645, 2022). "For example, a recent study showed that KRAS mutation plays an important role in the metabolic reprogramming of cancer cells, shifting them towards an anabolic metabolism and support unconstrained proliferation, leading to reduced activity of both gemcitabine and paclitaxel." (PMID 36551709, 2022). "In addition, the literature shows that PANC-1 is KRAS-independent whereas other cancers with KRAS mutations are KRAS-dependent." (PMID 35886918, 2022). "Mutations of Ras proteins such as KRas, which our method recognizes, cause cancer development." (PMID 36251702, 2022). "Since cancer cells are heavily addicted to glutamine, it is natural to observe that oncogenes, especially KRAS, elevate the genes associated with glutamine catabolism such GLS, GLUD, SLC1A5, transaminase, etc., through Myc, which is the downstream molecule of the oncogenes." (PMID 36613455, 2022). "Given that KRAS is mutated in human cancer more frequently than any other oncogene, the two products of the KRAS locus and the pathways they regulate are among the most attractive targets for anti-cancer drug discovery." (PMID 36393833, 2022). "The KRAS mutation is related closely to ferroptosis in several cancer cells." (PMID 35992146, 2022). "Among three isoforms, KRAS mutations cause most human cancers, with over 17% of all cancer types." (PMID 36619305, 2022). "To explore how specific cancers are driven by distinct KRAS mutations, we reasoned that effects unique to a mutation could be separated from those imparted by activation level by simply comparing two different oncogenic mutants expressed at high or low levels." (PMID 36069770, 2022).
cancer (continued). "Besides providing new therapeutic strategies to target KRAS-mutant cancer, sotorasib and adagrasib also provide a potential therapeutic rational to overcome KRAS secondary mutations mediating resistance to other therapies in other oncogenic driven NSCLC." (PMID 35251972, 2022). "Furthermore, KRAS, which encodes a GTPase downstream of the tyrosine kinase receptor, is an essential mediator for cancer cell growth, differentiation, and apoptosis." (PMID 36499051, 2022). "Furthermore, downstream phosphorylation of ERK) is inhibited in both MDA-MD-231 and PANC-1 cancer cell lines harboring KRAS mutations." (PMID 35886918, 2022). "Increasing evidence has shown that oncogenic mutations such as KRAS mutations are capable of mediating crosstalk with the immune system via oncogenic signaling and can lead to immune escape mechanisms at different stages of the cancer-immunity cycle." (PMID 35965494, 2022). "Studies showed that 30% of human malignant tumors were related to KRAS gene mutation." (PMID 35975176, 2022). "Cancer cells are entirely dependent on KRAS mutation which makes KRAS an oncogene." (PMID 35574217, 2022). "Specifically targeting KRAS mutants over KRAS wild-type would, in theory, minimize the toxicities and side effects associated with a potential pharmacotherapeutic agent, thus greatly enhancing its therapeutic index when treating cancer patients." (PMID 35045886, 2022). "Interestingly, KRAS-mutated cancer cells can upregulate PDL1 expression levels, which can be reversed with a selective KRASG12C inhibitor (ARS-853)." (PMID 35456940, 2022). "Across all cancers, non-G12/G13/Q61 codons constituted around 2% of total KRAS mutations." (PMID 35768438, 2022). "This combination has not been tested before; however, IF showed a synergistic effect with ascorbic acid vs. Kirsten rat sarcoma virus, a gene that makes a protein that is involved in cell signaling pathways that control cell growth, cell maturation, and cell death (KRAS) mutated cancers." (PMID 35859750, 2022). "The altered pathways may be associated with more significant cancer hallmarks induced by KRAS oncogenic effects." (PMID 35562390, 2022). "KRAS is among the most commonly mutated oncogenes in human cancer." (PMID 35954441, 2022). "Pan-cancer analysis also showed that a high level of KRAS is associated with poor outcomes." (PMID 35563733, 2022). "Unlike KRAS G12C–selective inhibitors, targeted inhibition of BCL6 might be effective in the majority of KRAS-mutant cancer subtypes and even in tumors harboring NRAS mutations." (PMID 36377663, 2022). "Introduction of the same KRAS mutations present in cancer patients into the genome of genetically engineered mouse (GEM) models is sufficient to induce LUADs that closely mimic those present in human patients once their expression is activated in the lungs of adult mice." (PMID 34951114, 2022). "At the same time, they can also promote cancer progression by releasing immunosuppressive signals, such as 8-OHdG and KRAS proteins that cause TAMs to differentiate into M2 phenotypes, as well as PGE2 that inhibits the functions of NK cells, DCs, and CD8(+) T cells." (PMID 36578477, 2022). "KRAS mutation is reportedly associated with poor prognosis in patients with different cancer types." (PMID 36139531, 2022). "We observed KRAS driven toxicity in multiple cancer types, and with different KRAS mutant alleles, including through ectopic expression of KRASG12C in H358, H23, and H1792 cells, and of KRASG12D in HCT 116 cells, which lead to decreased cell viability in all instances." (PMID 36418460, 2022).